EPHB4 (EPH receptor B4)
Diseases named in the same sentence as EPHB4 in open-access papers (continued):
Sharing a sentence is not in itself a finding about the gene and the disease.
tumor (continued). "Similarly, antibodies that target ephrin-B2 and the extracellular fibronectin type III domains of EphB4 have been shown to modulate angiogenesis and inhibit tumour growth by mechanisms that are still unclear." (PMID 25831049, 2015). "Importantly, both phenotypes can be restrained by stimulation with ephrin-B2 proving that over-production of EphB4 contributes in a ligand-independent mechanism and that ligand-dependent stimulation is tumour suppressive." (PMID 25831049, 2015). "Western blot analysis also confirmed markedly increased EphB4 expression in tumor specimens." (PMID 25148033, 2014). "Furthermore, 16 of the 18 tumor (89%) specimens showed an EphB4 signal, while 0 of 18 (0%) stained for EphB2." (PMID 25148033, 2014). "After the EphB4 extracellular domain is bound with vascular EphrinB2, it promotes angiopoiesis and endothelial cell migration and proliferation, thereby promoting tumor growth; whereas soluble sEphB4 inhibits tumor growth and angiopoiesis." (PMID 23596494, 2013). "Moreover, knockdown or inhibition of EphB4 attenuates the growth of cancer cells in vitro and in vivo, whereas introduction of wild-type EphB4 provides a gain of function in tumor cells." (PMID 23844053, 2013). "Antibodies to EphB4 have been described to inhibit tumor growth." (PMID 23251904, 2012). "The role of EphB4 and ephrin-B2 also extends to tumor growth and angiogenesis." (PMID 22292016, 2012). "Thus, an important role of EphB4 during tumor progression is to promote ephrin-B2 reverse signaling in the vasculature." (PMID 22194865, 2011). "Furthermore, overexpression of EphB4 in the mammary epithelium accelerated tumor onset and lung metastasis in MMTV-Neu animals." (PMID 21935409, 2011). "Additionally, ephrin-B2-induced EphB4 forward signaling in endothelial cells likely contributes to tumor angiogenesis." (PMID 22194865, 2011). "EphB4 and EphB6 were also significantly elevated in tumor epithelium relative to ‘normal’ samples." (PMID 21935409, 2011). "Thus, further analysis of EphB4 expression in both tumor parenchyma and the surrounding stroma is necessary, with human patient samples carefully stratified by stage and grade, as well as by molecular subtype and treatment regimen." (PMID 21935409, 2011). "To examine whether synchronous suppression of Dll4/Notch and EphB4/Ephrin-B2 signaling pathways might result in greater inhibition of RT2 tumor development, we treated RT2 Dll4+/- mice with sEphB4-Alb." (PMID 21092311, 2010). "Inhibition of EphB4 expression by specific siRNA or antisense oligonucleotides significantly inhibited tumour cell viability by inducing apoptosis via activation of caspase-8, and also inhibited tumour cell invasion and migration." (PMID 17353927, 2007). "In addition, EphB4-depleted tumours had a significant reduction in tumour microvasculature, consistent with an antiangiogenic effect of EphB4 knockdown in vivo." (PMID 17353927, 2007). "Here we show that progesterone, a known tumour suppressor also regulates EphB4 expression." (PMID 17353927, 2007). "In addition, there was significant induction of caspase-8 activity, and a much smaller induction of caspase-9 activity, indicating that EphB4 protects tumour cells from the extrinsic, membrane-originating apoptotic pathways." (PMID 17353927, 2007). "In addition, tumour cell-expressed EphB4 can interact with endothelial EphrinB2 to favour tumour vascularisation." (PMID 17353927, 2007). "We suspected that if EphB4 expression could promote tumour cell viability, it might also promote other features of malignant carcinomas, such as tumour migration and invasion." (PMID 17353927, 2007). "We hypothesized that induction of EphB4 is an early event required for tumor initiation." (PMID 40044981, 2025).
tumor (continued). "Our phopho-western blot data support that activating EphB4 while simultaneously avoiding activation of ephrinB2 using various therapeutic strategies such as the ephrinB2-Fc-His plasmid provides maximal benefit to reducing local tumor growth and distant metastases." (PMID 39489818, 2025). "Additionally, inhibition of the EphB4-ephrin-B2 pathway in experimental HNSCC models led to the reprogramming of the tumor immune microenvironment, suggesting that targeting this system could alter tumor ecology and reduce immune evasion." (PMID 40421081, 2025). "In addition, Prof. Jing-Ji Yang’s team reported a case of MET D1228N mutation in a patient with EPHB4-MET fusion on crizotinib and verified that the mutant tumor may be sensitive to tivantinib, a type III MET inhibitor, in a PDX mouse model." (PMID 38957460, 2024). "To further support a cancer cell-intrinsic tumor-suppressive effect of EphB4 that is independent of ephrinB2, we studied whether knockout of endothelial cell ephrinB2 expression can overcome the accelerated tumor growth observed in vivo following the knockout of EphB4 on cancer cells." (PMID 35725568, 2022). "Furthermore, EPHRIN B2 could be applied to the antigen-recognition domain of the CAR construct to harness EPHB4-expressing tumor cells to genetically modify CAR-T cells that lack the proliferative tendency of tumor cells via ligand-antigen interaction." (PMID 33816783, 2021). "Notably, 72.3% of the tumor samples showed significant expression of EphB4 (H-score ≥ 50)." (PMID 34298619, 2021). "To test if B16F10‐associated EphB4 activates tumor vascular EphrinB2, we generated syngeneic B16F10 tumors depleted of EphB4 and control tumors by infecting B16F10 cells with either a validated shRNA that effectively depletes EphB4 or with the control vector (pLKO)." (PMID 34102002, 2021). "Importantly, inhibiting EphB4 activation significantly attenuated the tumor-angiogenesis in vivo." (PMID 32850441, 2020). "Therefore, EphB4 suppression reduced tumor progression and increased apoptosis." (PMID 32795296, 2020). "Independent of interaction with EFNB2, EphB4 can be activated by ligand-independent pathways to promote proliferation and metastasis, as EphB4 mutants with mutated phosphorylation sites can still promote tumor cell growth and migration." (PMID 31949258, 2020). "Therefore, EphB4 is a promising target for tumor-targeting delivery in our system." (PMID 28942682, 2017). "Tumour cells expressing dominant negative EphB4 incapable of forward signaling but able to stimulate ephrin-B2 reverse signaling, attracted endothelial cells, stimulating cell invasion, survival and proliferation and this correlated with tumours with larger blood vessels and a higher blood content." (PMID 25831049, 2015). "EPHB4 plays a role in vascular development and may participate in tumor metastatic spread." (PMID 23251904, 2012). "Interestingly, elevated levels of ephrin-B2 have been reported in the remodeled blood vessels of tumors that recur after anti-angiogenic treatments and the soluble extracellular domain of EphB4 has been shown to disrupt tumor endothelial cell coverage by mural cells in vivo." (PMID 22194865, 2011). "This role may be fulfilled by EphB4 present in tumor cells or co-expressed in vascular cells." (PMID 22194865, 2011). "However, sEphB4-Alb treatment leads to fewer tumor blood vessels, suggesting that inhibition of Ephrin-B2/EphB4 pathway may reduce VEGF signaling even though VEGF level is increased." (PMID 21092311, 2010). "Therefore, EphB4/ephrinB2 may function in tumour advancement and coexpression of the Eph/ephrin system may potentiate tumour progression leading to poor survival." (PMID 18231102, 2008). "Coexpression of both EphB4 and ephrinB2 at high levels in malignancies including melanoma, neuroblastoma and cancers of the prostate, breast, lungs, oesophagus, gastrium, colorectum and uterine endometrium dysregulates cell adhesion and cell motility in tumours." (PMID 18231102, 2008).
tumor (continued). "Hence, apart from providing direct survival cues to tumour cells in vitro, EphB4 may also have a proangiogenic effect in vivo." (PMID 17353927, 2007). "Thus, overexpression of EphB4 by tumour cells may interrupt TRAIL-mediated apoptosis thus providing survival advantage to tumour cells." (PMID 17353927, 2007). "This may be because the EphB4 ectodomain exerted a chemoattractive effect on endothelial cells through ephrin-B2 expressed on these cells and promoted endothelial cell proliferation and survival resulting in more tumour vasculature." (PMID 16171530, 2005). "In particular EphB4, located at chromosome 7q22.1, and initially isolated from a human hepatocellular carcinoma cell line Hep3Ba has been reported by us and others to be highly expressed in many tumour tissues including colon, breast, endometrium, lung and head and neck." (PMID 16171530, 2005). "EPHB4-directed CAR T cells demonstrated enhanced cytotoxicity, proliferation, and cytokine secretion in vitro, and superior tumor control with increased T cell infiltration in Rh30-TACS tumors in vivo compared with Rh30 tumors." (PMID 42256207, 2026). "Thus, EphB4 loss may shift the balance of signaling and structural components to favor tumor proliferation and metastasis through non-classical EMT pathways that likely involve enhanced Wnt signaling and ECM remodeling." (PMID 39489818, 2025). "The researchers developed an EPHB4-CAR-T cell (product name AP8901) that can specifically recognize and kill malignant tumor cells expressing the EPHB4 receptor by modifying ephrin B2, the natural ligand of the EPHB4 receptor." (PMID 40842575, 2025). "Yet, the interaction between EphB4 and another RTK, namely platelet-derived growth factor receptor beta (PDGFRβ), in the presence of the PDGFRβ ligand, PDGF-BB, leads to tumor proliferation." (PMID 40508013, 2025). "By combining these technologies, it is possible to produce EPHB4-CAR-T cells that are rich in memory T cells, which define the anti-tumor effect of CAR-T cells, but which are less immune-depleting and more effective." (PMID 40842575, 2025). "Co-localization of EphB4/ephrin-B2 with CD34 in stromal microvessels and GFAP in tumor cells has been observed, with higher expression levels in poorly differentiated tumors, reinforcing its relevance to both tumor aggressiveness and vascular pathology." (PMID 41200151, 2025). "There are currently some drugs that target EPHB4, such as VANDETANIB, which is approved to inhibit tumour angiogenesis and tumour cellproliferation." (PMID 39036049, 2024). "We have reported that within the HNSCC tumor microenvironment (TME), EphB4 is predominantly expressed in cancer cells and its knockdown or knockout drives local progression by increasing immunosuppressive immune cells in the TME." (PMID 39091728, 2024). "To better understand the contribution of signaling triggered by EphB4 and ephrinB2 on tumor growth, we generated HNSCC cells expressing dominant-negative constructs of EphB4 and ephrinB2." (PMID 35725568, 2022). "EphB4 knockdown on CUHN013 cells resulted in a significant increase in cell growth compared to both the control and ephrinB2 knockdown tumor cells at varying time points." (PMID 35725568, 2022). "Endothelial cell rich tumor compartments, specifically, hyperplastic blood vessels and microvascular proliferative areas show increased EFNB2 and EPHB4 expression." (PMID 35629359, 2022). "Ephrin-type B-receptor 4 (EPHB4) was also identified as an alternative EPOR that triggers downstream signaling via STAT3 and promotes recombinant human EPO-induced tumor growth and progression." (PMID 34281163, 2021). "In this study, we aimed to determine the feasibility of using a lymphodepleted NHP model for the assessment of acute on‐target/off‐tumor toxicity after a single infusion of human peripheral blood mononuclear cell‐(PBMC)‐derived, EPHB4‐specific CAR‐T cells." (PMID 34123382, 2021).
tumor (continued). "We have utilised a natural ligand of EPHB4, Ephrin B2, as an antigen recognition site of the CAR molecule, and these CAR‐T cells effectively recognised and eliminated EPHB4‐positive tumor cells." (PMID 34123382, 2021). "Interestingly, immunohistochemical expression of EPHB4 in the venous endothelium and ephrin-B2 in the arterial endothelium was reported greater in tumoral areas compared with non-tumorous ones, possibly underlining the role of the EPH/ephrin system in tumor angiogenesis." (PMID 34445116, 2021). "Cellular experiments and mouse tongue xenograft models further confirmed that high EPHB4 expression promoted the proliferation and metastasis of OSCC tumours." (PMID 34539874, 2021). "Several groups have shown that the reverse EphB4 to EFNB2 signaling in endothelial cells plays an essential role in initiating angiogenesis and lymphangiogenesis, important processes in supporting tumor growth and metastasis." (PMID 31949258, 2020). "The results showed decreased EphB4 protein expression after HHT treatment both in HepG2 cells and tumor tissues." (PMID 32801343, 2020). "For in vivo test, an EphB4-overexpressing SMMC-7721 (EphB4+/7721) cell line was established and the anti-tumor effect of HHT on xenograft model of wild type SMMC-7721 (7721) cells and EphB4+/7721 cells was investigated." (PMID 32801343, 2020). "The soluble extracellular domain of EphB4, which disrupts the EphB4-EFNB2 interaction, attenuated angiogenesis and inhibited tumor growth." (PMID 31949258, 2020). "In this situation, disruption of EphB4-EphrinB2 interaction may represent a potential opportunity for anti-angiogenic cancer therapy, and on the other hand, a more efficient vasculature due to increased EphrinB2 signaling may at least facilitate delivery of anticancer drugs to tumor tissue." (PMID 29462967, 2018). "While antioncogenic EphB4/ephrin-B2 effects are mediated by activation of Abl-Crk pathway and downregulation of matrix metalloprotease MMP-2, its tumor promoting effects manifest via ligand-independent phosphorylation." (PMID 29682554, 2018). "EphB4 is a member of the receptor tyrosine kinase (RTK) family, which promotes tumor tissue development, oncogenesis and progression." (PMID 29207612, 2017). "We studied 80 primary and 12 metastatic ccRCC tumors and identified 7 peptide substrates with significantly increased tyrosine phosphorylation by metastatic samples relative to primary tumor samples including FGFR1, FAK1, ACHD, K2C8, EGFR, EPHB4 and MBP." (PMID 28418903, 2017). "In fact, we found previously that EphB4-EphrinB2 signalling activated in DLL4-expressing tumours is, to some extent, responsible for the increased vessel size and tumour resistance to anti-VEGF therapy." (PMID 28445154, 2017). "Another group of scientists identified ephrin-type B receptor 4 (EphB4) as an EPO receptor that triggers downstream signaling via STAT3 and promotes recombinant human EPO (rhEPO)-induced tumor growth and progression." (PMID 27164096, 2016). "Moreover, depending on the cell-environment conditions, EphB4 demonstrates the ability to be both a tumor promoter, when over-expressed and in the absence of stimulation by its sole cognate ligand, ephrin-B2, as well as a tumor suppressor stimulated by ephrin-B2." (PMID 25886373, 2015). "In vivo, EphB4 has also been demonstrated to provide a survival advantage to tumor cells, and, its inhibition has been shown to decrease the survival of the HNSCC tumor cells." (PMID 22523710, 2012). "The reduction of the average tumor volume was even more pronounced in sEphB4-Alb treated RT2 Dll4+/- group (approximately 90% reduction, p < 0.01) where Dll4/Notch and Ephrin-B2/EphB4 signaling were simultaneously inhibited." (PMID 21092311, 2010). "Reconstruction experiments were used to optimise immunomagnetic enrichment and RT-PCR detection of circulating tumor cells using four markers (ELF3, CK19, EGFR and EphB4)." (PMID 19961621, 2009).
tumor (continued). "However, human and murine EPH family proteins are highly conserved, and the EPHB4 CAR protein can bind with murine EPH family proteins, thus enabling the assessment of off-tumor toxicity in an immunodeficient murine xenograft model." (PMID 40842575, 2025). "Given the importance of axon-guided migration in GBM, we included inhibitors of Ephrin receptors (ALW-II-41–27 for EphA2, NVP-BHG712 for EphB4, and Ehp-inhibitor-1), and the CXCL12/CXCR4 axis (motixafortide), known to regulate directed migration in the hypoxic tumour core in immunotherapy." (PMID 41390851, 2025). "On the other hand, directly targeting the EphB4 through the inhibitory antibody, VasG3, failed to affect tumor progression." (PMID 40508013, 2025). "Notably, targeting the EphB4-ephrinB2 signaling axis with the engineered ligands ephrinB2-Fc-His and Fc-TNYL-RAW-GS reduces local tumor growth and distant metastasis in a preclinical model of HNSCC." (PMID 39489818, 2025). "An increase in EphB4 expression was seen in the tumor, while no expression was seen in normal prostate gland." (PMID 40044981, 2025). "EphB4 provides a survival advantage in tumor cells by further activating the PI3K pathway, unlike EphB2, which is expressed in normal gland and functions as a tumor suppressor." (PMID 40044981, 2025). "Specifically, monoclonal antibody mAb47 has shown efficacy in suppressing tumor angiogenesis and inhibiting the growth of both EphB4-positive and EphB4-negative tumors, suggesting its impact on the tumor microenvironment." (PMID 38811954, 2024). "HMGB1, being a nuclear nonhistone protein and an extracellularly secreted cytokine can interact with EPHB4, NF-κB, TLR4 and MIA, to promote cancer cell proliferation, migration, metastasis, innate immune response, and tumor escape while also affecting autophagy." (PMID 37511951, 2023). "Since we observed accelerated tumor growth in both CUHN013 EphB4 knockdown and EphB4 dominant-negative tumors, we investigated whether forward signaling via EphB4’s intracellular domain exerts a tumor-suppressive effect on tumor cell growth." (PMID 35725568, 2022). "We observed that Moc2 tumor cells lacking EphB4 treated with Dasatinib had half the mean tumor volume of the vehicle-treated group." (PMID 35725568, 2022). "In the control group where EphB4 is intact on the cancer cells, treatment with Nilotinib did not result in tumor growth reduction." (PMID 35725568, 2022). "Designing novel targeted therapeutics against ephrinB2 that can selectively access both tumor cells and the vasculature and performs its function without inhibiting its receptor EphB4 signaling will be critical to establish a meaningful effect on tumor growth." (PMID 35725568, 2022). "Given that the accelerated tumor growth observed with cancer cell knockdown of EphB4 was independent of stromal EphB4, we performed RNA-sequencing on Moc2 EphB4 knockdown tumors and control tumors to define the underlying cancer cell-intrinsic mechanisms." (PMID 35725568, 2022). "Our data showed that EphB4 knockout in the mouse collagen I-expressing cells such as fibroblasts did not mitigate the accelerated tumor growth." (PMID 35725568, 2022). "Regardless of the tumor model, a significant increase in tumor volume was observed when EphB4 was either knocked down or completely knocked out on cancer cells." (PMID 35725568, 2022). "Human EPHRIN B2 protein was able to bind with both murine EPHB4 and human EPHB4 at a similar level, indicating that our in vivo murine RMS tumor xenograft model may be utilized to ward off any possibility of off-tumor toxicity." (PMID 33816783, 2021). "On the other hand, TCC specimens exhibited gain of EPHB4 expression, which is absent in normal urothelium, with the signal strength correlating with the highest tumor stage." (PMID 34445116, 2021).